GET3 (guided entry of tail-anchored proteins factor 3, ATPase)
Description:
ATPase required for the post-translational delivery of tail-anchored (TA) proteins to the endoplasmic reticulum. Recognizes and selectively binds the transmembrane domain of TA proteins in the cytosol. This complex then targets to the endoplasmic reticulum by membrane-bound receptors GET1/WRB and CAMLG/GET2, where the tail-anchored protein is released for insertion. This process is regulated by ATP binding and hydrolysis. ATP binding drives the homodimer towards the closed dimer state, facilitating recognition of newly synthesized TA membrane proteins. ATP hydrolysis is required for insertion. Subsequently, the homodimer reverts towards the open dimer state, lowering its affinity for the GET1-CAMLG receptor, and returning it to the cytosol to initiate a new round of targeting. May be involved in insulin signaling.
Synonyms: ASNA1; TRC40; ARSA-I; ARSA1; ASNA-I; CMD2H
Tractability: PROTAC: ubiquitination databases record sites on it.
Target class: Enzyme; Hydrolase
Gene: Protein-coding gene on chromosome 19 (12,737,139 to 12,748,325, forward strand). Ensembl gene ENSG00000198356.
Subcellular location: Cytoplasm; Endoplasmic reticulum; Nucleus, nucleolus
Subcellular location (Human Protein Atlas): Nucleoli; Nucleoplasm
Pathways (Reactome):
Protein localization: Insertion of tail-anchored proteins into the endoplasmic reticulum membrane
Gene Ontology:
Molecular function: ATP hydrolysis activity; protein binding; protein carrier chaperone; ATP binding
Biological process: tail-anchored membrane protein insertion into ER membrane; protein insertion into ER membrane
Cellular component: cytoplasm; endoplasmic reticulum; extracellular exosome; GET complex; nucleolus; nucleoplasm; endoplasmic reticulum membrane
Genetic constraint (gnomAD): Loss-of-function variants: 15 observed, 31.48 expected, observed/expected ratio (o/e) 0.48, 90% interval 0.32 to 0.73. The upper end of that interval is the gene's LOEUF score, 0.73, which puts it in group 3 of 6, group 1 being the genes least tolerant of losing a copy. Missense variants: 333 observed, 461.85 expected, observed/expected ratio (o/e) 0.72, 90% interval 0.66 to 0.79. Synonymous variants: 198 observed, 182.87 expected, observed/expected ratio (o/e) 1.08, 90% interval 0.96 to 1.22.
Gene-disease validity (ClinGen):
ClinGen rates the evidence that GET3 causes each of these diseases.
cardiomyopathy, dilated, 2H (autosomal recessive): Limited.
Homologues: Orthologues: chimpanzee GET3 (100% identical), dog GET3 (100% identical), pig GET3 (100% identical), mouse Get3 (99% identical), rat Get3 (99% identical), guinea pig GET3 (99% identical), macaque GET3 (94% identical), zebrafish get3 (93% identical), tropical clawed frog get3 (92% identical), Drosophila melanogaster CG1598 (65% identical), Caenorhabditis elegans asna-1 (52% identical).
Diseases named in the same sentence as GET3 in open-access papers:
GET3 is named in the same sentence as 27 diseases in open-access papers, as found by Europe PMC text mining. Sharing a sentence is not in itself a finding about the gene and the disease. The quoted sentences say what the papers report.
type 2 diabetes (2 papers, 2022 to 2023). "Furthermore, loss of asna-1 causes insulin secretion defects in C. elegans and loss of Get3 in pancreatic β cells in mice leads to type 2 diabetes." (PMID 36939052, 2023).
epilepsy (1 paper, 2023). A brain disorder characterized by episodes of abnormally increased neuronal discharge resulting in transient episodes of sensory or motor neurological dysfunction, or psychic dysfunction. "Mutations TRC40 (GET3) in human are associated with diseases such as epilepsy and heart development." (PMID 36939052, 2023).
cancer (2 papers, 2021 to 2024). A tumor composed of atypical neoplastic, often pleomorphic cells that invade other tissues. "In mammals, the deletion of GET3 leads to embryonic lethality in mice, and upregulation of GET3 has been observed in several types of human cancers." (PMID 39596240, 2024).
GET3 also shares sentences with these, for which no sentence is quoted: cardiomyopathy (3 papers); heart disease (3); diabetes (2); infection (2); tumor (2); common variable immunodeficiency (1); congenital disorder of glycosylation (1); developmental delay (1); dilated cardiomyopathy (1); Emery-Dreifuss muscular dystrophy (1); hypersomnia (1); idiopathic cardiomyopathy (1); insomnia (1); Insulin resistance (1); lymphoma (1); melanoma (1); motor neuron disease (1); neurodegenerative disease (1); neutropenia (1); ovarian carcinoma (1); pancreatic agenesis (1); polycystic liver disease (1); tubulointerstitial kidney disease (1); viral infection (1).